USP43 (ubiquitin specific peptidase 43)
Description:
May recognize and hydrolyze the peptide bond at the C-terminal Gly of ubiquitin. Involved in the processing of poly-ubiquitin precursors as well as that of ubiquitinated proteins (By similarity).
Synonyms: FLJ30626
Tractability: PROTAC: its protein half-life has been measured.
Gene: Protein-coding gene on chromosome 17 (9,644,663 to 9,729,693, forward strand). Ensembl gene ENSG00000154914.
Subcellular location (Human Protein Atlas): Nuclear speckles; Nucleoplasm
Pathways (Reactome):
DNA Repair: Termination of translesion DNA synthesis
Gene Ontology:
Molecular function: ISG15-specific peptidase activity; cysteine-type deubiquitinase activity; cysteine-type peptidase activity; ubiquitin-like protein peptidase activity
Biological process: translesion synthesis; protein deubiquitination
Cellular component: nucleoplasm; nucleus
Genetic constraint (gnomAD): Loss-of-function variants: 32 observed, 71.43 expected, observed/expected ratio (o/e) 0.45, 90% interval 0.34 to 0.6. The upper end of that interval is the gene's LOEUF score, 0.6, which puts it in group 2 of 6, group 1 being the genes least tolerant of losing a copy. Missense variants: 1,274 observed, 1,332.1 expected, observed/expected ratio (o/e) 0.96, 90% interval 0.91 to 1. Synonymous variants: 598 observed, 552.18 expected, observed/expected ratio (o/e) 1.08, 90% interval 1.01 to 1.16.
Homologues: Orthologues: chimpanzee USP43 (99% identical), macaque USP43 (97% identical), mouse Usp43 (81% identical), rat Usp43 (81% identical), pig USP43 (80% identical), dog USP43 (79% identical), guinea pig USP43 (76% identical), rabbit USP43 (70% identical), tropical clawed frog usp43 (50% identical), zebrafish usp43a (48% identical), zebrafish usp43b (47% identical). Paralogues in human: USP31 (38% identical), USP19 (19% identical), USP24 (18% identical), USP32 (17% identical), USP15 (17% identical), USP4 (17% identical), USP9X (17% identical), USP6 (16% identical), USP9Y (16% identical), USP11 (16% identical), USP34 (14% identical), USP36 (13% identical), and 59 more.
Diseases named in the same sentence as USP43 in open-access papers:
USP43 is named in the same sentence as 25 diseases in open-access papers, as found by Europe PMC text mining. Sharing a sentence is not in itself a finding about the gene and the disease. The quoted sentences say what the papers report.
breast carcinoma (9 papers, 2021 to 2025). "USP43 has been explored as a suppressor of carcinogenesis in breast cancer and as an oncogene that promotes tumor progression in colorectal cancer and bladder cancer." (PMID 40890129, 2025). "In breast cancer, nuclear-localized USP43 binds to the NuRD complex and exerts tumor-suppressive effects by deubiquitinating H2BK120 and suppressing the transcription of EGFR, whereas cytoplasmic retention of USP43 contributes to tumor progression." (PMID 40890129, 2025). "The involvement of USP43 in breast cancer has been documented in two previous studies suggesting that Cav2.2 upregulates USP43 to promote tumorigenesis in breast cancer." (PMID 38613804, 2024). "Previous research indicates that USP43, a member of the USPs family, plays a significant role in breast cancer, CRC, lung squamous cell carcinoma, and nonsmall cell lung cancer can promotes tumor migration, invasion, and associated with a poor prognosis." (PMID 37050932, 2023). "Our study also revealed the functions of deubiquitinase USP43 in breast cancer cell migration, invasion, and metastasis." (PMID 36137995, 2022). "A subsequent investigation revealed a contrasting finding, suggesting that USP43 may function as a suppressive gene for breast cancer." (PMID 38613804, 2024). "USP43 facilitates breast cancer cell proliferation and cell cycle progression in vivo." (PMID 38087046, 2024). "Previous research has revealed that ubiquitin-specific protease 43 (USP43) can greatly influence breast cancer growth and metastasis by regulating EGFR/PI3K/AKT and that USP43 can also regulate the breast cancer cell cycle and epithelial–mesenchymal transition pathway, hence promoting tumorigenesis." (PMID 37050932, 2023). "To determine whether USP43 mediated the functions of Cav2.2, we introduced Cav2.2 shRNA and USP43 cDNA constructs into breast cancer cells." (PMID 36137995, 2022). "In addition, we showed that deubiquitinating enzyme USP43 stabilized cortactin and mediated the functions of Cav2.2 in invadopodia formation and metastasis in breast cancer." (PMID 36137995, 2022). "Therefore, it has been established that the USP43/NuRD complex inhibits the growth, invasion, and metastasis of breast cancer cells; thus, USP43 may serve as a suppressor of breast cancer." (PMID 38613804, 2024). "The stability of ZEB1 maintained by USP43 and USP51 promotes the proliferation and metastasis of colorectal and breast cancer." (PMID 36906615, 2023). "USP43 mediates Cav2.2 function by regulating cortical actin stability, extracellular matrix degradation, and migration, with Cav2.2 enhancing USP43 expression through NFAT2 activation, thus promoting breast cancer metastasis." (PMID 39048965, 2024). "Published studies have explored the connection between USP43 and various types of cancer, including osteosarcoma, non-small cell lung cancer, lung squamous cell carcinoma, breast cancer, and colorectal cancer." (PMID 38613804, 2024). "Further investigation into the underlying mechanisms of this procedure revealed that Cav2.2 regulates USP43 synthesis through NFAT2 dephosphorylation, thereby facilitating the promotion of cortactin and subsequent growth of invadopodia, ultimately leading to metastasis in breast cancer." (PMID 38613804, 2024). "In addition, USP43 could promote tumorigenesis by regulating cell cycle and EMT process in breast cancer." (PMID 33391437, 2021).
colorectal cancer (6 papers, 2019 to 2025). A primary or metastatic malignant neoplasm that affects the colon or rectum. "While in malignancies, USP43 drives the proliferation and metastasis of colorectal cancer and cervical cancer." (PMID 40890129, 2025). "In contrast, USP43 promotes colorectal cancer cell proliferation, migration, and invasion through its deubiquitination-mediated stabilization of ZEB1." (PMID 40890129, 2025). "USP43 promoted cell proliferation, migration and invasion of colorectal cancer, and reduce the sensitivity of chemotherapy through deubiquitinating ZEB1." (PMID 38087046, 2024). "According to this study, The expression of USP43 is significantly upregulated in colorectal cancer and correlates with an unfavorable prognosis." (PMID 38613804, 2024). "During the investigation into the role of USP43 in the pathogenesis of colorectal cancer, it has been revealed that USP43 exhibits a capacity to enhance in vitro proliferation, migration, and invasion of colorectal cancer cells." (PMID 38613804, 2024). "In summary, USP43 expression in colorectal cancer tissue was higher than those in the paired normal tissues." (PMID 33391437, 2021). "In this work, we have investigated the regulation of USP43 on colorectal cancer cells migration and invasion in USP43 knockdown in SW480 cells and USP43 overexpression in DLD1 cells." (PMID 33391437, 2021). "USP43 expression in colorectal cancer tissues was higher than those in the paired normal tissues (P<0.05)." (PMID 33391437, 2021). "In this study, we have investigated the effect of USP43 expression changes on chemotherapy sensitivity of colorectal cancer cells." (PMID 33391437, 2021). "Firstly, we had detected the expression of USP43 in colorectal cancer tissue and the paired normal tissues with the online dataset, western blot, qRT-PCR, and immunohistochemical staining analysis." (PMID 33391437, 2021). "To further probe the biological function of USP43 in colorectal cancer cells, we have studied USP43 expressions in five selected cell lines, including FHC, HCT116, SW480, DLD1, and LOVO." (PMID 33391437, 2021). "For instance, USP43 promoted cell proliferation, migration and invasion of colorectal cancer." (PMID 38087046, 2024). "USP43 is highly expressed in osteosarcoma and colorectal cancer." (PMID 38087046, 2024). "In addition, western blot analysis revealed that USP43 protein expression in colorectal cancer tissues was significantly higher than normal tissues." (PMID 33391437, 2021). "In summary, we demonstrated that high USP43 expression could be detected in colorectal cancer tissues and cells." (PMID 33391437, 2021). "USP43 also seems to participate in the control of colorectal cancer cell proliferation." (PMID 34571917, 2021). "In this study, we had examined the biological role of USP43 in colorectal cancer." (PMID 33391437, 2021). "USP43 could promote cell proliferation, invasion, and migration in colorectal cancer by regulating ZEB1 ubiquitylation degradation." (PMID 33391437, 2021). "Moreover, we have analyzed the distribution of the high USP43 expression in colorectal cancer tissue and the paired adjacent tissues." (PMID 33391437, 2021). "Therefore, USP43 emerges as a promising therapeutic target for the management of colorectal cancer, implying that the aberrant functioning of USP43 may contribute to the progression of this malignancy." (PMID 38613804, 2024). "However, there is still poor evidence about the role of USP43 in colorectal cancer." (PMID 33391437, 2021). "USP43 could promote the proliferation, migration, and invasion of colorectal cancer." (PMID 33391437, 2021). "The in vitro investigations have shown that USP43 stimulates the growth and spread of LUSC, which is consistent with its reported influence on breast and colorectal cancers." (PMID 38613804, 2024). "Meanwhile, USP43 can deubiquitinate and stabilize the ZEB1 protein, which plays an important role in the function of colorectal cancer." (PMID 33391437, 2021).
colorectal cancer (continued). "Therefore, it demonstrates that USP43 and ZEB1 govern the regulation of EMT, which plays a pivotal role in initiating and advancing colorectal cancer." (PMID 38613804, 2024). "Furthermore, the impact of USP43 on the susceptibility of colorectal cancer cells to chemotherapy, reveals a potential role for USP43 in upregulating ZEB1 expression and downregulating chemotherapy resistance in colorectal cancer." (PMID 38613804, 2024). "In addition, we have studied the effect of USP43 and ZEB1 on chemotherapy sensitivity of colorectal cancer." (PMID 33391437, 2021). "Meanwhile, qRT-PCR analysis indicated that USP43 expression in colorectal cancer tissues was significantly higher than that in the paired normal tissues (P<0.001)." (PMID 33391437, 2021). "Therefore, our results revealed that USP43 and ZEB1 can regulate EMT of colorectal cancer." (PMID 33391437, 2021). "Furthermore, immunohistochemical staining analysis indicated that USP43 expression in colorectal cancer tissue was significantly higher than that in the paired normal tissues (P<0.001)." (PMID 33391437, 2021).
ovarian carcinoma (5 papers, 2024 to 2025). A malignant neoplasm originating from the surface ovarian epithelium. "Our study provides inaugural evidence that USP43 orchestrates ferroptosis susceptibility in ovarian cancer, mechanistically delineating its governance of the FASN-HIF1α-SLC7A11 signaling axis." (PMID 40890129, 2025). "YY1 also stimulates the FASN-HIF1α pathway, causing ferroptosis suppression and the growth of ovarian cancer by inducing USP43." (PMID 41009346, 2025). "In order to verify the effectiveness of USP43 in an environment close to real human OC tissues, we constructed an ovarian cancer patients derived organoids (PDOs) model." (PMID 40890129, 2025). "To identify transcription factors promoting USP43 expression in ovarian cancer, we used the Alibaba2.1, Promo, AnimalTFDB, and TFbind databases to predict potential transcription factors binding to the USP43 promoter." (PMID 40890129, 2025). "This study aimed to screen all the USP family members and explored the specific function of USP43 in ovarian cancer." (PMID 40890129, 2025). "USP43 is an important prognostic factor for ovarian cancer, with its overexpression promoting ovarian cancer progression and its knockdown inhibiting it." (PMID 40890129, 2025). "The expression levels of USP family members in ovarian cancer were screened using bioinformatics analysis, and the specific function of USP43 was explored through in vitro and in vivo experiments." (PMID 40890129, 2025). "Further, ubiquitination assays showed that USP43 reduced FASN ubiquitination in ovarian cancer cell lines and The C110S mutant attenuated the ability of USP43 to hydrolyze ubiquitin chains on FASN." (PMID 40890129, 2025). "In our study, we have demonstrated that USP43 is a novel regulated target affecting ferroptosis in OC, providing a new option for targeting ferroptosis pathways to treat ovarian cancer." (PMID 40890129, 2025). "USP43 is markedly expressed in epithelial ovarian cancer, fostering cell proliferation, migration, invasion, and cisplatin resistance by stabilizing HDAC2 and activating the Wnt/β-catenin pathway." (PMID 39048965, 2024). "Hence, in this study, we aimed to identify the role and potential molecular basis of USP43 in ferroptosis in OC cells through in vitro and in vivo assays and provide new treatment options for ovarian cancer patients." (PMID 40890129, 2025). "This suggests that USP43 may serve as a promising therapeutic target for ovarian cancer, potentially offering efficacy with limited off-target effects." (PMID 40890129, 2025). "Nonetheless, the future development of highly specific USP43 inhibitors could offer a novel, safe, and effective therapeutic strategy for patients with ovarian cancer." (PMID 40890129, 2025). "As HDAC2 was reported to be highly expressed in ovarian cancer and associated with poor prognosis, we speculated that a regulatory relation may exist between HDAC2 and USP43." (PMID 38087046, 2024). "These discoveries underscore the clinical importance of USP43 in epithelial ovarian cancer, accentuating its potential as a therapeutic target to manage cancer progression, increase sensitivity to cisplatin chemotherapy, and ultimately enhance patient outcomes." (PMID 39048965, 2024). "Similarly, the protein expression of USP43, analyzed in clinical specimens of the human protein atlas, was barely expressed in normal ovarian tissues and highly expressed in ovarian cancer tissues." (PMID 38087046, 2024). "In addition, it was noted that ubiquitin-specific peptidase 43 (USP43) could reduce the sensitivity of epithelial ovarian cancer cells to cisplatin by activating the Wnt/β-catenin signalling pathway." (PMID 39857448, 2025). "This suggests that YY1 may affect the prognosis of ovarian cancer patients through USP43." (PMID 40890129, 2025). "However, it is unclear whether USP43 affects ferroptosis and through what mechanism it affects ferroptosis in ovarian cancer cells." (PMID 40890129, 2025).
ovarian carcinoma (continued). "Furthermore, the high expression of USP43 predicted a poor prognostic of ovarian cancer patients." (PMID 38087046, 2024). "Thus, USP43 might serve as a potential target for the control of ovarian cancer progression." (PMID 38087046, 2024). "Thus, targeting the USP43-FASN-HIF1α-SLC7A11 axis can inhibit ferroptosis and promote platinum sensitivity in ovarian cancer." (PMID 40890129, 2025). "In addition, studies have shown that USP43 mediates metastasis in breast and colon cancer, but it has not been reported in ovarian cancer metastasis or recurrence, and it will be a direction for our investigation in the future." (PMID 38087046, 2024).
bladder cancer (4 papers, 2024 to 2025). "While in bladder cancer, USP43 was found to have the ability to stabilize c-Myc to promote the glycolysis of cancer cells." (PMID 40890129, 2025). "Regulating glycolytic metabolism through targeting the c-Myc oncoprotein is demonstrated in the ubiquitin specific peptidase 43 (USP43) enzyme in bladder cancer." (PMID 39484162, 2024). "In bladder cancer, USP43 promotes glycolysis by regulating C-myc transcriptional activity." (PMID 40890129, 2025).
osteosarcoma (3 papers, 2021 to 2024). A usually aggressive malignant bone-forming mesenchymal neoplasm, predominantly affecting adolescents and young adults. "In investigating the role of USP43 in osteosarcoma, it was observed that patients with osteosarcoma displayed high levels of USP43, which contributes to the regulation of EMT, a critical cellular mechanism implicated in the progression of osteosarcoma." (PMID 38613804, 2024). "In patients with osteosarcoma and lung metastasis, USP43 deubiquitinates ZEB1 and maintains its transcription, resulting in increased invasion of osteosarcoma cells via inducing EMT." (PMID 38613804, 2024).
colon cancer (2 papers, 2021 to 2024). "For example, high expression of USP43 in breast and colon cancers has been shown to be associated with tumor development by increasing the ability of tumor cells to migrate." (PMID 34571917, 2021).
lung squamous cell carcinoma (2 papers, 2023 to 2024). "A recent study established a correlation between USP43 and lung squamous cell carcinoma (LUSC), indicating that USP43 facilitated LUSC proliferation and invasion, indicating an unfavorable prognosis." (PMID 38613804, 2024).
cholangiocarcinoma (1 paper, 2023). A carcinoma that arises from the intrahepatic biliary tree (intrahepatic cholangiocarcinoma) or from the junction, or adjacent to the junction, of the right and left hepatic ducts (hilar cholangiocarcinoma). "USP43 expression was higher in tumor tissues than in normal tissues in several types of tumors, including pancreatic adenocarcinoma (PAAD), rectum adenocarcinoma (READ), colon adenocarcinoma (COAD), cholangiocarcinoma (CHOL), stomach adenocarcinoma (STAD), and esophageal carcinoma (ESCA)." (PMID 37050932, 2023).
clear cell renal carcinoma (1 paper, 2024). A malignant epithelial neoplasm of the kidney characterized by the presence of lipid-containing clear cells within a vascular network. "To further validate these findings, we examined the effect of USP43 loss in clear cell renal carcinoma cell (ccRCC) lines that have constitutive activation of both HIF-1 and HIF-2 (RCC4 cells, HIF-1α+, HIF-2α+ and VHL−), or only encode HIF-2α (786-0 cells, HIF-1α−, HIF-2α+ and VHL−)." (PMID 39009674, 2024).
gastric cancer (1 paper, 2024). A primary or metastatic malignant neoplasm involving the stomach. "USP43 promotes gastric cancer progression by stabilizing STIP1 through deubiquitination." (PMID 39605891, 2024).
Huntington disease (1 paper, 2022). Huntington disease (HD) is a rare neurodegenerative disorder of the central nervous system characterized by unwanted choreatic movements, behavioral and psychiatric disturbances and dementia. "Other genes highlighted by this study include CD320, which was reported to be associated with Huntington’s disease in a previous EWAS; USP43, which was shown to have DNAm levels associated with progressive supranuclear palsy; APBA2, which was reported in an EWAS of Parkinson’s disease (PD)." (PMID 36359320, 2022).
lung adenocarcinoma (1 paper, 2021). A carcinoma that arises from the lung and is characterized by the presence of malignant glandular epithelial cells. "Overexpression of USP43 or knockout of USP43 can affect the proliferation, migration, and stemness of lung adenocarcinoma cells." (PMID 33391437, 2021).
mesothelioma (1 paper, 2023). A usually malignant and aggressive neoplasm of the mesothelium which is often associated with exposure to asbestos. "Interestingly, lower expression of USP43 is significantly associated with poor survival outcomes in patients with mesothelioma." (PMID 36657447, 2023). "The expression and chromatin analyses at genes such as USP43, HOXA6, HOXA10, and USP18 demonstrate that these genes are downregulated via PRC2-mediated silencing in BAP1-deficient mesothelioma." (PMID 36657447, 2023).